MRPL51 (mitochondrial ribosomal protein L51)
Synonyms: bMRP64; MRP64; CDA09; HSPC241; mL51
Tractability: Small molecule: a structure with a bound ligand is known. PROTAC: its protein half-life has been measured.
Gene: Protein-coding gene on chromosome 12 (6,491,886 to 6,493,846, reverse strand). Ensembl gene ENSG00000111639.
Subcellular location: Mitochondrion
Subcellular location (Human Protein Atlas): Mitochondria; Nucleoli
Pathways (Reactome):
Metabolism of proteins: Mitochondrial ribosome-associated quality control; Mitochondrial translation elongation; Mitochondrial translation initiation; Mitochondrial translation termination
Gene Ontology:
Molecular function: protein binding; structural constituent of ribosome
Biological process: mitochondrial translation; translation
Cellular component: mitochondrial large ribosomal subunit; mitochondrial ribosome; mitochondrion; mitochondrial inner membrane
Genetic constraint (gnomAD): Loss-of-function variants: 7 observed, 16.92 expected, observed/expected ratio (o/e) 0.41, 90% interval 0.23 to 0.78. The upper end of that interval is the gene's LOEUF score, 0.78, which puts it in group 3 of 6, group 1 being the genes least tolerant of losing a copy. Missense variants: 155 observed, 177.47 expected, observed/expected ratio (o/e) 0.87, 90% interval 0.77 to 1. Synonymous variants: 65 observed, 62.98 expected, observed/expected ratio (o/e) 1.03, 90% interval 0.84 to 1.27.
Homologues: Orthologues: chimpanzee MRPL51 (99% identical), macaque MRPL51 (95% identical), rabbit MRPL51 (84% identical), mouse Mrpl51 (81% identical), pig MRPL51 (81% identical), guinea pig MRPL51 (80% identical), dog MRPL51 (80% identical), rat Mrpl51 (70% identical), tropical clawed frog mrpl51 (57% identical), zebrafish mrpl51 (53% identical), Drosophila melanogaster mRpL51 (37% identical), Caenorhabditis elegans mrpl-51 (32% identical).
Diseases named in the same sentence as MRPL51 in open-access papers:
MRPL51 is named in the same sentence as 8 diseases in open-access papers, as found by Europe PMC text mining. Sharing a sentence is not in itself a finding about the gene and the disease. The quoted sentences say what the papers report.
lung carcinoma (3 papers, 2020 to 2022). "Immunohistochemistry data of the three model gene proteins (MRPL51, SLK, PRC1) were retrieved from the HPA database and their expression was found to be upregulated in lung cancer." (PMID 35982906, 2022).
ovarian carcinoma (1 paper, 2025). A malignant neoplasm originating from the surface ovarian epithelium. "MRPL51 and MRPL52 are upregulated in ovarian cancer patients, with the low expression of both MRPL51 and MRPL52 associated with a worse prognosis." (PMID 39859078, 2025).
cancer (2 papers, 2022 to 2023). A tumor composed of atypical neoplastic, often pleomorphic cells that invade other tissues. "Among these, MLF2, COPS7A, PEX5, DDX47, STRAP and MRPL51 displayed strong correlations with USP5 in most cancer types." (PMID 37268697, 2023). "The Genomics of Drug Sensitivity in Cancer (GDSC) database and the Cancer Therapeutics Response Portal (CTRP) were used to evaluate the sensitivity and resistance of SLK, MRPL51, and PRC1-targeting drugs." (PMID 35982906, 2022).
MRPL51 also shares sentences with these, for which no sentence is quoted: tumor (2 papers); Alzheimer disease (1); hypothyroidism (1); Sepsis (1); tauopathy (1).